AKT1 (AKT serine/threonine kinase 1)
Diseases named in the same sentence as AKT1 in open-access papers (continued):
Sharing a sentence is not in itself a finding about the gene and the disease.
breast cancer (continued). "For instance, AKT1 which is associated with ovarian cancer, breast cancer, colorectal cancer and schizophrenia was classified as a phenodiv gene while TYRP1 which is associated with brown albinism and rufous albinism was classified as a phenosim gene." (PMID 20525321, 2010). "A study in 280 postmenopausal Swedish women with breast cancer indicated that expression of pAkt was significantly associated with both Akt1 and Akt2 staining; however, the correlation was stronger for Akt1 than for Akt2." (PMID 18184439, 2008). "The AKT1 E17K mutation was found in 5 out of 61 (8.2%) breast cancers, 3 out of 51 (5.9%) colorectal cancers and 1 out of 50 (2.0%) ovarian cancers." (PMID 18392055, 2008). "This study demonstrated that the AKT1 E17K mutation occurs in breast cancers at a low frequency, and that it is rare in other common cancers, including colorectal, lung, gastric and hepatocellular carcinomas and acute leukaemias." (PMID 18392055, 2008). "Notably, hyperactivation of Akt1 has been observed in approximately half of breast cancers, often attributed to mutations or amplifications within the PI3K/Akt/mTOR axis." (PMID 40798865, 2025). "Additionally, AKT1 has been linked to progestin resistance in endometrial and breast cancers by reducing progesterone receptor expression." (PMID 40028534, 2025). "Notably, the E17K activating mutation, located in the PH domain of AKT1, is a hotspot mutation in the Chinese breast cancer population, with a carrier rate of 3.1%, and accounting for 90.9% of all AKT1 mutations in luminal A subtypes." (PMID 40206206, 2025). "Additionally, a hot‐spot Akt1‐E17K mutation has been detected in pleckstrin homology domain of AKT1 which was linked to progression of ovarian and breast cancers." (PMID 38336976, 2024). "Notably, the prevalence of AKT1 mutations is notably higher in specific breast cancer subtypes, particularly HR+ and HER2− tumors." (PMID 38172946, 2024). "Studies indicate that breast cancer patients harboring AKT1 mutations may exhibit distinct clinical features and outcomes." (PMID 38172946, 2024). "Similarly, the AKT1 rs1130233-AA genotype was strongly linked to breast cancer susceptibility with an OR = 3.20, (95%) CI = 1.682–6.084, RR = 3.69, and p < 0.044." (PMID 36831624, 2023). "Breast cancer tumour tissue reveals AKT1 and MTOR mutations." (PMID 36831624, 2023). "Besides, AKT1 E17K mutation accelerates cell migration and resistance to chemotherapeutic treatments in luminal breast cancer cells." (PMID 35402264, 2022). "AKT1-E17K mutation in breast cancer can isolate β-catenin to the cell membrane, which decreases ZEB1 transcription and leads to an increase in E-cadherin expression and the reversal of epithelial-mesenchymal transformation, thus inhibiting tumor migration and invasion." (PMID 36060002, 2022). "Their findings show that targeted therapies against uncommon HER2 and AKT1 mutations have clinically relevant activity, indicating that these mutations could be used to treat breast cancer." (PMID 35887191, 2022). "In this study, we present experimental evidence that AKT1E17K is a bona fide oncogene for mammary epithelium, being able to efficiently initiate breast cancer in mice by using a ROSA26-based engineered mouse model for the expression of the oncogenic AKT1(E17K) mutation in the mammary gland." (PMID 35681625, 2022). "The AKT1 (E17K) activating mutation is also detected in 3.6% of these breast cancers." (PMID 34975329, 2022). "Therefore, activation of the PTEN-PI3K-AKT1 pathway by either PTEN loss or PIK3CA or AKT1 activating mutations induces breast cancer development." (PMID 34975329, 2022). "In addition, E17K hotspot is the most characteristic mutation of the Akt1 which is a recurrent somatic mutation observed in breast cancer, colorectal cancer, lung cancer and ovarian cancer." (PMID 36180910, 2022).
breast cancer (continued). "Thus, increased Akt1 SUMOylation as a result of SENP3 deficiency modulates polarization of macrophages to the M2 subtype within a breast cancer microenvironment, which in turn promotes tumor progression." (PMID 33932085, 2022). "Interestingly, a W80R mutation in AKT1 has been detected in patients with uterine, colon, and breast cancer, albeit at lower frequencies than the activating mutation E17K." (PMID 35440108, 2022). "Thus, our finding that AKT1 mutations are associated with HER2-negative status in breast cancer agrees with those of a previous study." (PMID 34670536, 2021). "On the other hand, a report from China also showed that AKT1 mutations were found in 7.1 and 8.2% of breast cancer patients, suggesting that AKT1 mutations may be particularly common in Asians." (PMID 34670536, 2021). "Akt1 E17K mutation was restricted to hormone receptor-positive luminal breast cancers." (PMID 34298660, 2021). "Previous studies have also found that AKT1 mutations are closely related to breast cancer." (PMID 34408553, 2021). "PIK3CA and AKT1 gene mutations are observed in numerous types of cancers, including breast cancer." (PMID 33669698, 2021). "A single amino acid substitution, E17K, in the lipid-binding PH domain of AKT-1 is a recurrent somatic cell mutation that occurs in breast cancer, meningioma, colorectal, endometrial, and ovarian cancers, and the mutation results in constitutive AKT1 activation." (PMID 33572326, 2021). "And breast cancer patients had a longer survival time in the AKT1 mutation group." (PMID 34408553, 2021). "While Akt1 E17K may serve as an oncogene in some luminal breast cancers, additional mutations may be required to promote tumorigenesis." (PMID 34298660, 2021). "Moreover, analysis of patient samples identified Akt1 as a major contributor of metastatic lymph node involvement which is a risk for breast cancer progression." (PMID 34298660, 2021). "Among them, the prognostic analysis of AKT1 gene mutation was most related to breast cancer." (PMID 34408553, 2021). "The overall prevalence of AKT1 mutations was 23 (7.4%) of 311 breast cancer samples." (PMID 34670536, 2021). "Notably, the Chinese breast cancer patients harbored a higher frequency of actionable AKT1 mutations than the Caucasian breast cancer patients." (PMID 33173047, 2020). "However, in breast cancer models, loss of Akt2 inhibited, while loss of Akt1 accelerated, cell motility and metastasis in both in vitro and mouse breast cancer models." (PMID 33110146, 2020). "Similarly, as novel breast cancer susceptibility genes, we found AKT1, ESR2, and RAD50 as the top genes." (PMID 33376724, 2020). "Our results demonstrate clinically relevant activity of targeted therapies against rare HER2 and AKT1 mutations, confirming these mutations could be targetable for breast cancer treatment." (PMID 32919527, 2020). "AKT1 germline mutations are mainly associated with Cowden syndrome, characterized by the appearance of hamartomas, and an increased risk of developing multiple cancers, especially breast cancer." (PMID 32858845, 2020). "L52R is the second leading mutation found in AKT1 in breast cancer." (PMID 31752925, 2019). "In contrast, in the myoepithelial normal breast cancer cells growth, migration, survival and protein biosynthesis are reduced among mutated AKT1 and the transformed myoepithelial cancer cells with the E17K mutation exhibit a similar phenotype except of a missing effect on cell survival." (PMID 31752925, 2019). "The importance of C77 is reinforced by the activating breast cancer-associated Akt1-C77F mutation." (PMID 31792197, 2019). "Likewise, the stem cell-like phenotype in AKT1 knockdown breast cancer cells is linked to the EMT caused by low levels of miR-200." (PMID 31752925, 2019). "The hypothesis about the dichotomy gained further confirmation from data of clinical breast cancer probes reporting an association of low AKT1 with a reduced metastasis-free survival." (PMID 31752925, 2019).
breast cancer (continued). "Because of the anti-metastatic effect of AKT1 in breast cancer, a loss of AKT1 expression or activity at least in a subpopulation of the primary tumor could be a possible mechanism for the initiation and development of metastases." (PMID 31752925, 2019). "Another study by the same group linked Akt1 activity to palladin, an actin-binding protein that anchors cytoskeletal proteins to actin fibers thus reducing reduced stress fiber formation and attenuating breast cancer cell invasion in vitro." (PMID 31360736, 2019). "In mouse and human breast cancer cells, the overactivation of AKT1 has been associated with ductal-like tumor growth but other studies showed that AKT1 could inhibit epithelial-to-mesenchymal transition and BC metastasis." (PMID 31781306, 2019). "Despite the small sample size, we found that the intronic variant, AKT1 rs3803304, may act as a predictive biomarker in the risk of developing breast cancer in the high altitude Ecuadorian mestizo population." (PMID 30065942, 2018). "AKT1 mutations have been reported in 1.4% to 8% (average ~4%) invasive ductal breast carcinoma, and the oncogenic mutant loci E17K in AKT1 has been considered as a potential diagnosis biomarker of breast cancer." (PMID 28301567, 2017). "Both methods are employed at central testing labs for prospective or retrospective identification of the AKT1 E17K mutation in ER+ breast cancer patients in the context of a clinical trial testing the AKT inhibitor AZD5363 in combination with endocrine (fulvestrant) therapy." (PMID 28472036, 2017). "The AKT1 promoter mutation, methylation and expression may play distinct roles in breast cancer and could be potential biomarkers for breast cancer diagnosis and classification." (PMID 28301567, 2017). "Although AKT1 E17K mutation is rare, it was demonstrated to be a driver mutation for breast cancer, thereby suggesting the potential of the E17K mutation as a diagnostic mutation for breast cancer." (PMID 29140300, 2017). "Knockdown of AKT1 rescues cell migration defect in PIPP-deficient breast cancer cells." (PMID 28082369, 2017). "In the mutation analysis, we found somatic mutation (AF>5%) in 24.2% of breast cancer patients (23 in 95) indicating that AKT1 promoter mutation may be a frequent event in breast cancer." (PMID 28301567, 2017). "Interestingly, in breast cancer AKT1(E17K) is mutually exclusive with PIK3CA and PTEN mutations, although in other cancers such as endometrial carcinoma, these mutations frequently co-exist in the same tumor." (PMID 27004402, 2016). "To study the functional significance of the AKT1(E17K) mutation in breast cancer, we developed a system to stably express either wild-type AKT1 or AKT1(E17K) in a doxycycline-inducible manner in the non-tumorigenic immortalized MCF10A breast epithelial cell line." (PMID 27004402, 2016). "It is hypothesized that AKT1 is a driver mutation in breast cancer which could be supported by identification of patients bearing no other known cancer-causing mutations." (PMID 27515171, 2016). "The frequency of the AKT1(E17K) mutation in breast cancers ranges from 4-8%." (PMID 27004402, 2016). "However, SomInaClust also prioritized driver genes that are less frequently mutated in breast cancer like AKT1 (20 out of 772 mutations) and CDKN1B (7 mutations, representing less than 1% of all mutations across samples)." (PMID 25903787, 2015). "The hotspot AKT1 E17K mutation occurs in approximately 3% of primary breast cancers." (PMID 25277176, 2014). "Whether the variant, Skp2B will be phosphorylated by p-Akt1 and affect biological function of breast cancer cells needs to be further studied." (PMID 23300741, 2012). "Although coexistent mutations of AKT1 and PIK3CA mutations are suggested to be infrequent in breast cancer, it remains to be elucidated whether AKT1 mutations are mutually exclusive with all the other PI3K–AKT-activating alterations in various tumour types." (PMID 19491896, 2009).
breast cancer (continued). "Since there are multiple drug targets in this pathway, including PIK3CA inhibitors, which are approved for breast cancer, and AKT1 inhibitors, the lower prevalence of mutations in this pathway may lead to worsening disparities in outcomes, as these treatments would not be efficacious in this group." (PMID 41162424, 2025). "Capivasertib (AZD5363) shows a constructive pharmacokinetic and toxicity profile in a BT474c breast cancer xenograft mouse model and exhibits a promising efficacy in targeting castration resistant prostate cancer, Her2+ breast cancer models and tumors harboring the Akt1 E17K mutation." (PMID 36180910, 2022). "Moreover, by reconstructing a disease–gene network containing 749 PTM substrates, 275 diseases, and 1437 disease–gene interactions, breast cancers are found to have the largest number of associated PTMs, while the important protein kinase AKT1 has the largest numbers of connected diseases." (PMID 30244175, 2018). "However, the mutation spectrum in promoter region of AKT1 in breast cancer is still unclear." (PMID 28301567, 2017). "One study revealed that the AKT1(E17K) somatic mutation occurs early in breast tumor progression, and therefore one can speculate that subsequent and additional genetic lesions are required for AKT1(E17K) to function as an oncogene in breast carcinoma." (PMID 27004402, 2016). "The AKT inhibitor capivasertib is approved in combination with fulvestrant for PIK3CA/AKT1/PTEN-altered advanced breast cancer following results from the CAPItello-291 trial." (PMID 41201834, 2026). "Of the three AKT isoforms (AKT1, AKT2 and AKT3), AKT1 and AKT2 are the most prominently associated with human breast cancer initiation and progression." (PMID 41408399, 2025). "Our study is one of the largest analytical studies of pathogenic alterations in PI3K/AKT pathway genes (PIK3CA, AKT1, AKT2, AKT3, and PTEN) among patients with breast cancer." (PMID 40597213, 2025). "Disrupting this cycle by combining an AKT1 inhibitor with a STING agonist has been shown to reduce tumor proliferation in mouse models of endocrine-resistant breast cancer." (PMID 40244377, 2025). "Tier I/II mutations were detected in 481 (36%) of all breast cancer samples, the majority of which (279/58%) having ≥1 mutation in the PI3K/AKT pathway (PIK3CA, AKT1, and PTEN) (20% total cohort frequency)." (PMID 41590338, 2025). "In the PI3K/AKT pathway, options include Capivasertib (used in metastatic breast cancer with PIK3CA/AKT1/PTEN alterations), RLY-2608 (PIK3CA inhibitor), and PI3Kβ inhibitors like GSK2636771 and AZD8186." (PMID 41301024, 2025). "PIK3CA and Akt1 gene mutations are frequently observed in breast cancer, with PIK3CA mutations primarily being detected in HER2+ve and ER+ve breast cancer." (PMID 39858015, 2025). "To identify lncRNAs binding to the AKT1E17K mutant protein, we transfected Flag‐tagged AKT1 wild‐type (AKT1WT) or E17K mutant (AKT1E17K) plasmids into breast cancer cell line MDA‐MB‐231." (PMID 40135844, 2025). "Loss of function mutations in the tumour suppressor PTEN, or homozygous deletion of PTEN are observed in 5–10% of ER+ breast cancers and genetic activation of AKT-1 occurs in 5–7% of ER+ breast cancers." (PMID 40263319, 2025). "In breast cancer tissues, SVIL‐AS1 is highly expressed and associated with p‐AKT1 level and poor prognosis of patients." (PMID 40135844, 2025). "In HR+/HER2- breast cancer, 8.7% (87 of 995) of hotspot alterations associated with an on-label matched therapy were detected at a VAF <5%, comprising alterations in AKT1, ESR1, PIK3CA, and PTEN." (PMID 40711866, 2025). "The phosphorylation level of FDX1‐S63 highly correlated with AKT1 activity in both breast cancer cell lines and tumor tissues." (PMID 39976173, 2025). "Over-activation of this pathway occurs in approximately half of luminal-type breast cancers owing to activating mutations in PIK3CA and AKT1 and inactivating alterations in PTEN." (PMID 39466567, 2025).
breast cancer (continued). "Alteration of this pathway occurs via mutations in oncogenes, such as the catalytic subunit of the class I PI3K (PIK3CA) or AKT1, in ~40% and ~7% of estrogen receptor positive (ER+) breast cancers, respectively." (PMID 41408399, 2025). "Despite this, 93% of metastasis-specific mutations in putative metastatic driver genes remained undetected within primary tumors, as did 96% of metastasis-specific mutations in known breast cancer drivers, including ERRB2 V777L, ESR1 D538G, and AKT1 D323H." (PMID 38321573, 2024). "Enhanced AKT1 SUMOylation upon SENP3 loss resulted in AKT1 hyperphosphorylation and activation, thereby facilitating M2 polarization, breast cancer cell proliferation and metastasis." (PMID 39127633, 2024). "Capivasertib is approved for use in combination with fulvestrant for patients with advanced breast cancer whose tumors have one or more PIK3CA/AKT1/ PTEN alterations." (PMID 39510293, 2024). "The panel was applied to samples from HR+ breast cancer cell lines with known activating PIK3CA or AKT1 alterations published in COSMIC (RRID:SCR_002260)." (PMID 38954770, 2024). "AKT1 (v-AKT Murine Thymoma Viral Oncogene Homolog 1) has emerged as a prospective predictive biomarker in breast cancer, offering valuable insights into disease prognosis and treatment response." (PMID 38172946, 2024). "Studies like the STIC-CTC and DETECT-III trials emphasize the predictive value of CTC quantity and characteristics and genomic analysis of CTCs has revealed mutations in genes such as AKT1 and PIK3CA, crucial for targeted breast cancer treatments." (PMID 39304879, 2024). "For example, breast cancer cell migration and invasion are promoted by Akt2 but suppressed by Akt1, both in vitro and in vivo." (PMID 38291468, 2024). "Our finding revealed that local anesthetic ropivacaine attenuated breast cancer stemness through AKT1/GGT1/NF-κB signaling pathway, suggesting the potential clinical value of ropivacaine in breast cancer treatment." (PMID 38523299, 2024). "Mechanistically, hyperactivated AKT1 blocked the formation of STING/TBK1/IRF3 trimer in endocrine‐resistant breast cancer." (PMID 39023171, 2024). "Further studies show that AKT2 is related to breast cancer metastasis, and AKT1 plays an important role in the local cancer initiation process." (PMID 38542870, 2024). "Both AKT1 and AKT2 have been implicated in breast cancer previously, with some mixed results regarding their specific function." (PMID 39057065, 2024). "TRIB3 has been reported to mediate breast cancer (BC) proliferation and metastasis by interacting with AKT1, and blocking the interaction between TRIB3 and AKT1 can inhibit the progression of BC." (PMID 39881875, 2024). "Combined with our findings that hyperactivated AKT1 blocked cGAS‐STING signaling, we proposed that inactivated STING signaling and hyperactivated AKT1 formed a positive feedback loop in endocrine‐resistant breast cancer." (PMID 39023171, 2024). "Proteins that differed between the patient groups were subsequently quantified in AKT1- or PIK3CA-altered breast cancer cell lines with varying capivasertib sensitivity." (PMID 38954770, 2024). "Nevertheless, it is crucial to validate these computational predictions through in vitro and in vivo studies to thoroughly evaluate the therapeutic potential and viability of these compounds for AKT1-targeted breast cancer treatment." (PMID 39275052, 2024).